BCL11B (BCL11 transcription factor B)
Diseases named in the same sentence as BCL11B in open-access papers (continued):
Sharing a sentence is not in itself a finding about the gene and the disease.
hepatocellular carcinoma (3 papers, 2020 to 2023). A malignant tumor that arises from hepatocytes. "B‐cell lymphoma/leukemia 11B (BCL11B) expression in hepatocellular carcinoma relates to chemosensitivity and clinical prognosis." (PMID 37293953, 2023). "BCL11B has been confirmed as a tumor suppressor in hepatocellular carcinoma with inhibitory effects on proliferation, cell cycle progression, apoptosis, and mobility." (PMID 36376973, 2022). "Low BCL11B expression was an independent indicator for shorter overall survival and time to recurrence for patients with hepatocellular carcinoma." (PMID 36376973, 2022). "Our results indicated that overexpression of BCL11B amplifies GATA6 expression in hepatocellular carcinoma in vitro and in vivo that leads to anti‐apoptotic signal activation, and induces resistance to chemotherapy, which influenced the postoperative prognosis." (PMID 37293953, 2023). "Thus, in this study, we examined the molecular characterization of BCL11B expression in hepatocellular carcinoma." (PMID 37293953, 2023). "Microarray and real‐time PCR analyses in hepatocellular carcinoma cell lines indicated a correlation between BCL11B and GATA6, a gene reported to be correlated with oncogenic activities and resistance to anthracycline, which is often used for hepatocellular carcinoma chemotherapy." (PMID 37293953, 2023). "The cumulative progression‐free survival and overall survival were significantly longer in the clinical cases of BCL11B‐negative hepatocellular carcinoma than BCL11B‐positve cases." (PMID 37293953, 2023). "Many malignancies were reported to exhibit changes in BCL11B gene expression; however, no study has focused on the relationship between BCL11B and hepatocellular carcinoma, which potentially exhibits DNA replication stress and damages upon its oncogenesis." (PMID 37293953, 2023). "Although BCL11B was preferentially decreased and low BCL11B expression indicated poorer prognosis in LIHC (liver hepatocellular carcinoma) cohort according to TCGA database, its exact function in HCC remained elusive." (PMID 33093445, 2020).
ischemia (3 papers, 2013 to 2024). A hypoperfusion of the BLOOD through an organ or tissue caused by a PATHOLOGIC CONSTRICTION or obstruction of its BLOOD VESSELS, or an absence of BLOOD CIRCULATION. "In attempt to clarify the functional consequences of BCL11B over-expression after ischemia we quantified the co-expression with previously proven markers of beneficial and damaging processes after brain ischemia." (PMID 37237015, 2023). "Taken together, an increase of BCL11B and SATB2 after ischemia was accompanied with their positive correlations with the functional recovery and negative correlations with ischemic damage, suggesting their beneficial role in brain ischemia." (PMID 37237015, 2023). "Similarly, since the expressions of both BCL11B and SATB2 were increased in the contralateral hemisphere after ischemia, this is also where we identified the highest frequency of their co-expression." (PMID 37237015, 2023). "Likewise, the increase of BCL11B and SATB2 co-expression after ischemia correlated with the lesion reduction and neurological recovery rates suggesting their combined effect on functional recovery." (PMID 37237015, 2023). "Furthermore, BCL11B and SATB2 expression positively correlated with neurological recovery rate suggesting their beneficial role in damage repair after ischemia." (PMID 37237015, 2023).
Neurodevelopmental delay (3 papers, 2019 to 2024). "BCL11B mutations in humans are associated with neurodevelopmental delay, overall learning deficits as well as impaired speech acquisition and autistic features." (PMID 38358390, 2024). "Patients with BCL11B mutations present with neurodevelopmental delay, overall learning deficits as well as impaired speech acquisition and autistic features." (PMID 38358390, 2024).
osteosarcoma (3 papers, 2022 to 2025). A usually aggressive malignant bone-forming mesenchymal neoplasm, predominantly affecting adolescents and young adults. "Genes involved in epithelial cell proliferation, such as BCL11B, NRAS, THBS1, and VEGFC, promote angiogenesis and tumorigenesis, reflecting the heterogeneity of osteosarcoma-related genes." (PMID 35610231, 2022).
prostate carcinoma (3 papers, 2016 to 2025). A carcinoma that arises from epithelial cells of the prostate gland. "This may be explained by TMED10's role as a biomarker of favorable prognosis in prostate cancer and BCL11B's function as a tumor suppressor." (PMID 41472855, 2025). "Genes in NK cells (i.e., BCL11B for T-ALL, MAP3K7IP2 for prostate cancer) and in monocytes (i.e., LCK and BCL11B for T-ALL, PDCD1LG2 for Hodgkin’s lymphoma, PRDM16 for AML, CACNA1D for prostate cancer) were found significant in our meta-EWAS." (PMID 38466776, 2024).
severe combined immunodeficiency (3 papers, 2023 to 2024). Severe combined immunodeficiency (SCID) comprises a group of rare monogenic primary immunodeficiency disorders characterized by a lack of functional peripheral T lymphocytes resulting in early-onset severe respiratory infections and failure to thrive. "Constitutive BCL11B mutations can result in human multiorgan system dysfunction and severe combined immunodeficiency (SCID)." (PMID 36918563, 2023). "BCL11B is related to a neurodevelopmental disorder, severe combined immunodeficiency, and AD-like skin inflammation phenotype." (PMID 37180101, 2023).
age-related hearing loss (2 papers, 2013 to 2024). "Our study revealed that BCL11B gene polymorphisms were significantly associated with age-related hearing loss." (PMID 38829888, 2024). "Recently, Bcl11b was associated with age-related hearing loss and was suggested to be required for OHC survival and normal hearing." (PMID 23472202, 2013). "Age-related hearing loss is a complex disease caused by a combination of genetic and environmental factors, and a study have conducted animal experiments to explore the association between BCL11B heterozygosity and age-related hearing loss." (PMID 38829888, 2024).
Autoimmunity (2 papers, 2021 to 2022). The occurrence of an immune reaction against the organism's own cells or tissues. "Here the authors use an early T cell-specific Bcl11b-deficient mouse that develops autoimmunity through a population of nonconventional MR1-restricted T cells and characterise their function." (PMID 36376329, 2022).
Cognitive impairment (2 papers, 2021 to 2024). Abnormal cognition is characterized by deficits in thinking, reasoning, or remembering. "Genes involved in the cognitive impairment MAG, GDF15, GPR176, and EPHB1 (upregulated), BCL11B, GIMAP7, and ACOD1 (downregulated) were differentially expressed." (PMID 38755198, 2024).
colon cancer (2 papers, 2022 to 2024). "To functionally address the role of Bcl11b in tumor formation, we deleted Bcl11b in LoVo cells, a colon cancer cell line carrying APC mutation." (PMID 39433900, 2024). "The chromatin regulator Bcl11b promotes intestinal epithelium regeneration and the onset of colon cancer by activating Wnt signaling and inhibiting NuRD complex activity." (PMID 39433900, 2024). "As Bcl11b is a nuclear protein and activated the Wnt reporter in APC-mutated colon cancer cells, we hypothesized that it might work downstream of β-catenin." (PMID 39433900, 2024). "Furthermore, Bcl11b deletion impairs tumorigenesis of colon cancer cells." (PMID 39433900, 2024). "BCL11B up-regulates NKG2D ligands of the major histocompatibility complex class I-related molecules A and B (MICA and MICB), promotes the anti-tumor response of T- and NK-cells and prevents immune evasion of colon cancer cells." (PMID 36600891, 2022).
epidermoid carcinoma (2 papers, 2009 to 2010). "Of note, BCL11B was found to be co-expressed with the cancer stem cell marker BMI-1 in a subset of undifferentiated squamous cell carcinoma cases and cell lines." (PMID 20824091, 2010).
gastric cancer (2 papers, 2013 to 2021). A primary or metastatic malignant neoplasm involving the stomach. "However, the relationship between hsa-miR-337-3p and BCL11B and their role in gastric cancer metastasis needs to be further determined." (PMID 24422944, 2013).
immunodeficiency 49 (2 papers, 2020 to 2022). Any primary immunodeficiency disease in which the cause of the disease is a mutation in the BCL11B gene. "It is widely known that BCL11B-related disorder can lead to two phenotypes with common features, namely, type 49 immunodeficiency and intellectual development disorders with malformation, speech delay, and T-cell abnormalities." (PMID 36176959, 2022).
inflammatory bowel disease (2 papers, 2018 to 2024). A spectrum of small and large bowel inflammatory diseases of unknown etiology. "Mice lacking BCL11B in double‐positive thymocytes develop inflammatory bowel disease, with massive pro‐inflammatory cytokine‐producing CD4+ T cells infiltrating in the colon." (PMID 39092763, 2024). "For example, the colons of mice lacking BCL11B display significant levels of infiltrated proinflammatory T helper type 1 (Th1) and Th17 CD4+ T cells, neutrophils and macrophages and develop inflammatory bowel disease." (PMID 30089823, 2018).
multiple myeloma (2 papers, 2019 to 2022). "Neither the expression nor the function of BCL11B in myeloma cells is known." (PMID 36230837, 2022).
myelodysplastic syndrome (2 papers, 2021 to 2022). A clonal hematopoietic disorder characterized by dysplasia and ineffective hematopoiesis in one or more of the hematopoietic cell lines. "BCL11B was identified as an important role in T-cell function, and its lower expression is associated with adverse clinical outcomes for patients with myelodysplastic syndrome." (PMID 35204331, 2022).
myeloid leukemia (2 papers, 2016 to 2025). A clonal proliferation of myeloid cells and their precursors in the bone marrow, peripheral blood, and spleen. "Since 14q32 rearrangements deregulating BCL11B define a distinct subtype of T-/myeloid-MPAL and immature myeloid leukemia, we assessed BCL11B expression." (PMID 41057686, 2025).
T cell neoplasms (2 papers, 2020 to 2022). "Since, to date, no specific BCL11B inhibitor has been invented, this model can be used as a proof of principle for the rationale of therapeutic BCL11B suppression in T cell neoplasms." (PMID 35563322, 2022). "It has been shown by us and others that BCL11B is overexpressed in T cell neoplasms and that suppression of BCL11B using siRNA leads to massive apoptosis of malignant T cells but not normal T lymphocytes." (PMID 33384022, 2020).
adenoma (1 paper, 2024). A neoplasm arising from the epithelium. "Bcl11b has been reported to repress intestinal epithelium regeneration and adenoma formation by inhibiting the Wnt/β-catenin pathway as the Bcl11bKO/+;Apcmin/+ mice developed more adenoma than the Apcmin/+ mice." (PMID 39433900, 2024).
Anxiety (1 paper, 2022). Intense feelings of nervousness, tension, or panic often arise in response to interpersonal stresses. "Bcl11b deletion did not alter anxiety-like behavior in the elevated plus maze." (PMID 36289639, 2022).
atrial fibrillation (1 paper, 2025). A disorder characterized by an electrocardiographic finding of a supraventricular arrhythmia characterized by the replacement of consistent P waves by rapid oscillations or fibrillatory waves that vary in size, shape and timing and are accompanied by an irregular ventricular response. "In the selection of feature genes for atrial fibrillation, LDHB, DPEP2, BCL11B, CKAP4, RORA, PFKFB2, and CXCR4 were identified as potentially important predictors, with the model error being lowest when the number of genes reached eleven." (PMID 41359645, 2025).
brain ischemia (1 paper, 2023). Diminished or absent blood supply to the brain caused by obstruction (thrombosis or embolism) of an artery resulting in neurologic damage. "This complementarity of their function was also reflected in the BCL11B and SATB2 distribution after brain ischemia." (PMID 37237015, 2023). "Immunohistochemistry revealed a spatial pattern of BCL11B and SATB2 expression after brain ischemia and the results were quantified by measuring integrated optical density of the labelled cells." (PMID 37237015, 2023). "Despite the substantial over-expression of both ATF3 and HDAC2 after brain ischemia, only the increase in ATF3 and BCL11B co-expression was observed, while BCL11B and HDAC2 co-expression was not altered, indicating increase of BCL11B was associated with the beneficial processes after brain ischemia." (PMID 37237015, 2023). "BCL11B increase was observed over both brain hemispheres, however SATB2 increase after brain ischemia was predominant in the contralateral hemisphere that was not directly affected by ischemic damage." (PMID 37237015, 2023).
breast tumor (1 paper, 2024). "We therefore determined to address whether the senescent mammary cells caused by Bcl11b loss are vulnerable to cancer transformation with the DMBA-induced breast tumor formation assay for WT and Bcl11b-KO cells." (PMID 38886378, 2024).
cardiac hypertrophy (1 paper, 2020). "A study published in 2014 showed that BCL11B (alias CTIP2) might be associated with cardiac hypertrophy (HCM)." (PMID 32790701, 2020).
cerebral palsy (1 paper, 2023). A group of disorders affecting the development of movement and posture, often accompanied by disturbances of sensation, perception, cognition, and behavior. "In addition to extending the abnormal phenotype on MRI, our patient was the second to be diagnosed with cerebral palsy among BCL11B variant patients." (PMID 36683525, 2023).
cervical cancer (1 paper, 2020). A primary or metastatic malignant neoplasm involving the cervix. "This detected a subgenomic, URR‐E6‐E7‐E1 segment of HPV70 DNA, a type not generally associated with cervical cancer, inserted in an intron of the B‐cell lymphoma/leukemia 11B (BCL11B) gene in the human genome." (PMID 31407403, 2020).
colitis (1 paper, 2024). Inflammation of the colon. "In DSS-induced colitis model, Bcl11b knockout also led to more pronounced body weight loss, increased epithelium damage, as well as impaired cell proliferation." (PMID 39433900, 2024).
colon adenocarcinoma (1 paper, 2024). "Consistently, the two separate GSE datasets of endoscopically procured gut mucosal biopsies from cancer patients showed Bcl11b expression was markedly increased in colon adenocarcinoma (COAD) and rectum adenocarcinoma (READ) compared with normal samples." (PMID 39433900, 2024).
congenital diaphragmatic hernia (1 paper, 2021). A posterolateral defect of the diaphragm that allows passage of abdominal viscera into the thorax, leading to respiratory insufficiency and persistent pulmonary hypertension with high mortality. "Using clinical whole exome sequencing (WES), we found a BCL11B missense variant in a patient with a left-sided congenital diaphragmatic hernia as well as sagittal suture craniosynostosis." (PMID 34900871, 2021).
cutaneous T-cell lymphoma (1 paper, 2020). "Mycosis fungoides (MF) is an additional skin cancer type where Bcl11b expression was analyzed, which accounts for almost 70% of cutaneous T-cell lymphoma (CTCL)." (PMID 33363142, 2020).
demyelinating disorders (1 paper, 2018). "Moreover, our in vitro and in vivo findings provide important information for the development of an effective cell therapeutic strategy for demyelinating disorders via the downregulation of Bcl11b expression." (PMID 29416501, 2018).
dyslexia (1 paper, 2024). A learning disorder characterized by an impairment in processing written words. "We found that several of the individual genetic loci that dispose most significantly to dyslexia were associated with the volumes of primary auditory cortices (Heschl’s gyri), including PPP2R3A, BCL11B, SATB2, and SH2B3." (PMID 39693421, 2024).
Dystonia (1 paper, 2025). An abnormally increased muscular tone that causes fixed abnormal postures. "Notable examples include cases of KMT2B-related dystonia caused by a coding mutation not captured by WES and BCL11B-related dystonia resulting from copy number variants that were difficult to detect using standard exome techniques." (PMID 40722357, 2025).
gastric lymphoma (1 paper, 2016). An extranodal lymphoma that arises from the stomach with the bulk of the mass located in the stomach. "28S rRNA has been identified as a novel fusion partner of carcinoma-related genes such as BCL6, BCL11B, IGKV3-20, and COG1 in gastric lymphoma or hematopoietic tumors." (PMID 27517048, 2016).
HCMV infection (1 paper, 2024). "Furthermore, FcRT cells had downregulation of BCL11B, which regulates the development of CD8+ T cells with NK identity in chronic HCMV infection." (PMID 39531313, 2024).
head and neck cancer (1 paper, 2012). A primary or metastatic malignant neoplasm affecting the head and neck. "COUP-TF interacting protein 2 [(Ctip2), also known as Bcl11b] is an important regulator of skin homeostasis, and is overexpressed in head and neck cancer." (PMID 22383956, 2012).
HPRT-deficiency (1 paper, 2014). "All the previous results clearly established that Bcl11b and DARPP-32 have a role in HPRT-deficiency." (PMID 24804781, 2014).
Hypertension (1 paper, 2018). The presence of chronic increased pressure in the systemic arterial system. "Together with previous evidence, our results encourage further research into the role of BCL11B in pathophysiology of human hypertension." (PMID 29973135, 2018).
i.p. (1 paper, 2016). "As in the i.p. infection model, proliferation of CD8+ T cells in the spleen was reduced in the absence of Bcl11b, whereas proliferative responses of mucosal effector CD8+ T cells were largely unaffected." (PMID 27790219, 2016).
inborn error of immunity (1 paper, 2024). A disorder in which the immune system is unable to mount an adequate immune response. "Several germline heterozygous BCL11B variants have been identified in human patients with inborn errors of immunity (IEI) patients." (PMID 38495886, 2024).
liver cancer (1 paper, 2020). An epithelial or non-epithelial malignant neoplasm that arises from the liver. "Low BCL11B expression was significantly associated with advanced Edmondson stage (P = 0.012) and Barcelona Clinic Liver Cancer (BCLC) stage (P = 0.031)." (PMID 33093445, 2020).
melanoma (1 paper, 2025). A malignant, usually aggressive tumor composed of atypical, neoplastic melanocytes. "BCL11B has been closely linked to SKCM progression and treatment, particularly in melanoma brain metastases." (PMID 40547036, 2025). "Melanoma-specific gene regulatory networks have identified BCL11B as a potential therapeutic target, offering new strategies for personalized immunotherapy and targeted treatments." (PMID 40547036, 2025).
Motor delay (1 paper, 2025). A type of Developmental delay characterized by a delay in acquiring motor skills. "Haploinsufficiency of BCL11A and BCL11B has been implicated in the development of NDDs, including ID, developmental speech delay, motor delay, and ASD." (PMID 40124112, 2025).
myeloid neoplasm (1 paper, 2023). Proliferation of myeloid cells originating from a primitive stem cell. "While the CDK6 gene is known to be a critical regulator of normal and leukemic stem cells, the involvement of BCL11B in myeloid neoplasms is unusual." (PMID 37046792, 2023).
Neonatal sepsis (1 paper, 2018). Systemic inflammatory response to infection in newborn babies. "TSPO, ZAP70, CEBPB targeting MAPK14, has-miR-150 targeting BCL11B might affect the pathogenesis of neonatal sepsis." (PMID 30497506, 2018). "In the miRNA-DEG regulatory network, BCL11B was targeted by has-miR-150, suggesting that has-miR-150 might be involved in the pathogenesis of neonatal sepsis by targeting BCL11B." (PMID 30497506, 2018). "Besides, TSPO, ZAP70, CEBPB targeting MAPK14, has-miR-150 targeting BCL11B might act in the pathogenesis of neonatal sepsis." (PMID 30497506, 2018).